CXCL1 (C-X-C motif chemokine ligand 1)
Diseases named in the same sentence as CXCL1 in open-access papers (continued):
Sharing a sentence is not in itself a finding about the gene and the disease.
leukemia (10 papers, 2013 to 2026). A malignant (clonal) hematologic disorder, involving hematopoietic stem cells and characterized by the presence of primitive or atypical myeloid or lymphoid cells in the bone marrow and the blood. "Many of the treatment failure–associated cytokines (e.g., SIRT1 and CXCL1) could support leukemia stem cell proliferation and survival." (PMID 36047494, 2022). "The roles of C-X-C motif ligand 1 (Cxcl1) and C-C motif chemokine ligand 2 (Ccl2) in the development of various cancers, including leukemia, have been well documented." (PMID 41550719, 2026). "In hepatic LAMs, the majority of M1-associated genes, including CCL5, CXCL1, IL-12β, iNOS, and TNF-α, exhibit increased expression during leukemia progression." (PMID 38779660, 2024). "The chemokine-receptor axes play parts in development of leukemia, CXCL1, CXCL10 and CXCL12 are involved in immune responses." (PMID 34711015, 2021). "Here, the authors show that mesenchymal stem cells-derived PML is involved in the maintenance of leukemia cells through Cxcl1 and IL6 and that PML inhibition enhances sensitivity to chemotherapy." (PMID 29302031, 2018). "Therefore, as a future work the designing of leukemia animal models with employing recombinant CXC chemokines CXCL1, CXCL10 and CXCL12 is proposed for the examination of the role and ability of these chemokines in control of AML complications." (PMID 34711015, 2021). "Moreover, among the soluble factors regulated by Pml, Cxcl1, and Il6 seem to play an important role in the progression of the leukemia." (PMID 29302031, 2018). "CML red pulp macrophages (RPMs) are able to produce a variety of cytokines and chemokines such as IL-10, CCL3, CCL4, CCL5, CXCL1, TNF-α, and SCF, to sustain leukemia initial cells (LICs)." (PMID 38779660, 2024). "Ex vivo experiments from different research groups indicate that leukemia stimulation of primary BM-MSCs is able to specifically upregulate the expression of CCL2, CXCL10, CCL22, CXCL8, and CXCL1." (PMID 33922612, 2021). "We found that CXCL1, CXCL6, TEP1, IL8, CCL2 and PTGS2 genes were the most up-regulated genes in BMSCs co-cultured in the direct contact with leukemia cells." (PMID 24304929, 2013). "While CXCL1 has not previously been measured during febrile episodes in children with leukemia, CXCL8 has been extensively studied." (PMID 37919603, 2024). "Specifically, TNF-α mediates increased CXCL1 expression in CML BMSCs through signal transduction pathways, interacting with highly expressed CXCR2 in LSCs, thereby inducing a CXCR2 selection-dependent mechanism leading to the unlimited expansion of LSCs and leukemia progenitor cells." (PMID 40427609, 2025). "Interestingly, these chemokines, abundant in leukemia-conditioned MSC supernatants, were able to potently attract B-ALL cells that, besides CXCR4, showed high membrane levels of CCR4 (CCL22 and CCL2 receptor) and variable levels of CXCR1/2 (CXCL1 and CXCL8 receptors)." (PMID 33922612, 2021).
lung disease (10 papers, 2015 to 2025). "In particular, plasma CXCL1 has been suggested as a good peripheral biomarker of lung disease." (PMID 26204894, 2015). "Importantly, all these results in DO mice mimic studies in humans with TB, such that CXCL1 appears to be a good peripheral biomarker of lung disease, and cytokines and the ratios are weak but significant correlates." (PMID 26204894, 2015). "Previously, we described elevated levels of cytokines/chemokines such as IL-18, IFN-γ, CXCL-10, CXCL-9, G-CSF, IL-6, CXCL-1, VEGF, and PDGF-BB in plasma samples of tuberculosis (TB) patients with active pulmonary disease." (PMID 37685858, 2023). "When evaluated in samples from human patients, CXCL1 achieved the World Health Organization’s targeted profile for a triage diagnostic test, discriminating active TB from important clinical differential diagnoses: latent Mtb infection and non-TB lung disease in HIV-negative adults." (PMID 34403447, 2021). "When tested in human sera, only CXCL1 met the WHO’s TPP triage diagnostic test criteria, successfully discriminating active pulmonary TB (ATB) from LTBI; from non-TB lung disease; and from normal sera." (PMID 34403447, 2021). "CXCL1 maintained high AUCs, successfully discriminating ATB from LTBI (0.972) and ATB from non-TB lung disease (0.921)." (PMID 34403447, 2021). "One protein biomarker, serum CXCL1, met the World Health Organization’s Targeted Product Profile for a triage test to diagnose active TB from latent M. tb infection (LTBI), non-TB lung disease, and normal sera in HIV-negative, adults from South Africa and Vietnam." (PMID 34403447, 2021). "The best performing protein biomarker, CXCL1 had high sensitivity and specificity to diagnose HIV-negative, adults with ATB in high burden countries (South Africa and Vietnam), and discriminate those patients from the important clinical differential diagnoses: LTBI and non-TB lung disease." (PMID 34403447, 2021).
oral cancer (10 papers, 2011 to 2025). "Oral cancer has been linked to pro-inflammatory cytokines, such as CXCL1 and IL-1β." (PMID 35626430, 2022). "CAF-derived CXCL1 contributes significantly to inducing dormancy in OSCC cells and simultaneously facilitates oral cancer cell motility and invasiveness, which is closely linked to unfavorable clinical outcomes, especially in cases of tongue carcinoma." (PMID 40490643, 2025). "Bioinformatics analyses identified CXCL1 as a hub gene with significant protein–protein interactions in oral cancer, particularly in OSCC and oral tongue squamous cell carcinoma." (PMID 40490643, 2025). "Among the top 20 proteins showing relatively high expression in SCC25 cells, we focused on CXCL1, which was recently reported to be significant in oral cancer." (PMID 40490643, 2025). "In oral cancer CXCL1 has been suggested to have a role in tumor progression since in patient samples the expression of CXCL1 has been shown be associated with leukocyte infiltration, lymph node metastasis, and angiogenesis." (PMID 24204919, 2013). "For oral cancer, IL6 (sensitivity = 84, specificity = 72, ROC Area = 0.8816, threshold = 1.074) and CXCL1 (sensitivity = 86.67, specificity = 86.96, ROC Area = 0.8812, threshold = 0.1386) expression reached the threshold sensitivity and specificity for a strong biomarker." (PMID 38175424, 2024). "Meanwhile, stimulation with CXCL1 did not affect the proliferative capacity of oral cancer cells." (PMID 39132161, 2024).
thyroid cancer (10 papers, 2018 to 2024). "In thyroid cancer, tumor cell-derived soluble factors facilitated in vitro mast cell activation and recruitment, and the mast cell-producing mediators, especially CXCL1, most effectively enhanced the growth, survival, and invasion of cancer cells." (PMID 35764974, 2022). "An indirect role for CXCL1 in thyroid cancer progression was hypothesized in a study performed on mast cells." (PMID 29977225, 2018). "CXCL1 may be important in the formation or function of brain metastasis in thyroid cancer." (PMID 38673949, 2024). "Another source of CXCL1 in thyroid cancer tumors may be mast cells." (PMID 38673949, 2024). "In brain metastatic papillary thyroid carcinoma tumors, there is a higher expression of CXCL1 than in non-brain metastatic papillary thyroid carcinoma tumors or primary brain tumors, which indicates some association between this chemokine and brain metastasis in thyroid cancer." (PMID 38673949, 2024). "According to transcriptome sequencing, antitumor chemokine regulatory genes (CXCR3) were upregulated, and protumor chemokine regulatory genes (CCR3, CXCL1, CXCL2, CXCL3, CXCL8, and CXCR2) were downregulated after MWA in thyroid cancer." (PMID 38779358, 2024). "Histamine, IL-6, IL-1, TNF-α, and chemokines such as CXCL1/GRO-α, CXCL8/IL-8, and CXCL10/IP-10 are secreted from mast cells when thyroid cancer cells are activated." (PMID 36293435, 2022). "A mouse xenograft study has suggested histamine, CXCL1/GRO-α and CXCL10/IP-10 as TMC secreting factors that are important in thyroid cancer cell proliferation." (PMID 36293435, 2022). "Several researchers have additionally demonstrated that four chemokines, CXCL1, CCL5, CCL20 and CCL21, biologically affect thyroid cancer cells by modulating inflammation and the immune microenvironment." (PMID 33345267, 2021). "MCs also produce a broad spectrum of chemokines (CXCL8/IL-8, CCL25/TECK, CXCL10/IP-10, CXCL1/GRO-α), interleukins (IL-6), and other molecules (TNF-α) that are involved in the epithelial-to-mesenchymal transition (EMT) activation of thyroid cancer cells." (PMID 34204889, 2021). "At present, CCL2, CCL15, CCL20, CXCL1, CXCL8, CXCL12, and CXCL16 are the main chemokines showing a role in thyroid cancer." (PMID 29977225, 2018). "Studies taking into account the role of CCL15, C–X–C motif ligand 12, CXCL16, CXCL1, CCL20, and CCL2 in the context of thyroid cancer will be reviewed with particular emphasis on CXCL8." (PMID 29977225, 2018). "This was observed for CXCL1 and CXCL6 in breast invasive carcinoma, PPBP in kidney chromophobe, CXCL3 in kidney renal papillary cell carcinoma, CXCL6 in pancreatic adenocarcinoma, CXCL6 in thyroid carcinoma, and CXCL3 in thymoma." (PMID 37686093, 2023). "Moreover, mast-cell-derived mediators: histamine, CXCL1 and CXCL10 could increase thyroid cancer cell survival and DNA synthesis in vitro." (PMID 30808413, 2019).
acute respiratory distress syndrome (9 papers, 2017 to 2025). Progressive and life-threatening pulmonary distress in the absence of an underlying pulmonary condition, usually following major trauma or surgery. "The M1 pathway is similar to the pathology of acute respiratory distress syndrome (ARDS), leading to increased expression of interleukin (IL)-8 and CXCL1 and increased neutrophil recruitment via the CXCR2 receptor." (PMID 36814205, 2023). "CXCR2 is a receptor for a number of chemokines such as the GRO family (CXCL1-3) and CXCL8, all of which are elevated in respiratory inflammatory diseases such as COPD, severe asthma, and acute respiratory distress syndrome." (PMID 28596972, 2017). "In this vein, during acute respiratory distress syndrome (ARDS), recruited alveolar neutrophils and Mos/macrophages acquire a classically activated phenotype (Mo1/M1) responsible for the release of several growth factors and proinflammatory cytokines, including CXCL1, CXCL2, CXCL10, CCL2, and TNF-α." (PMID 39940787, 2025).
adenoma (9 papers, 2011 to 2023). A neoplasm arising from the epithelium. "Surprisingly, we also find that some stem cell-associated genes such as ALDH1L1 and CXCL1/3 are increased in the MDA34ad-TVA adenoma sample, suggesting a stem cell phenotype." (PMID 27100181, 2016). "They found that CXCL1 was higher in primary adenocarcinomas (n = 132), adenomas (n = 32), and metastases (n = 52) than in normal colon epithelium(P < 0.001)." (PMID 28415702, 2017). "We observe that elevated CXCL1 mRNA expression in human occurs throughout the adenoma-adenocarcinoma sequence with early induction in 77% of adenomas." (PMID 26104296, 2015). "We have elucidated a complementary adaptive response to serum deprivation by human CRC epithelial cells and myofibroblasts, thereby maintaining high tumorigenic CXCL1 level in the tumor microenvironment throughout the adenoma-adenocarcinoma sequence." (PMID 26104296, 2015). "Of particular note, CXCL-1 was significantly induced in both human and murine cells, with this chemokine highly implicated in the pathogenesis of CRC, playing a role in the adenoma-adenocarcinoma sequence (77% of cases), angiogenesis and recruitment of pro-tumorigenic stromal cells." (PMID 35365751, 2022). "We observed an increased expression of the neutrophil chemoattractant CXCL1 in wild type mice, whose expression has been shown to increase in adenomas and adenocarcinomas, indicating a more advanced dysplastic lesions/ACFs, which is supported by our immunohistochemistry data." (PMID 28410235, 2017). "Analysis of TNF-α, CXCL1, IL-1β, IL-10 protein and TGF-β mRNA levels in colonic tissue segments devoid of obvious adenomas revealed the expected increases in these cytokines in the AOM/DSS mice were not affected by M(IL4) treatment." (PMID 34691050, 2021). "In situ hybridization for two selected transcripts (CA7, CXCL1) was performed on NAT (n = 3), adenoma (n = 3) and CRC (n = 3) FFPE samples." (PMID 26208990, 2015). "CXCL1, CXCL2, CXCL3, CCL20, and IL-8 had increased expression in the adenoma and adenocarcinoma compared to normal colonic mucosa." (PMID 21249124, 2011).
co-infection (9 papers, 2012 to 2025). "MHV co‐infection in ZBP1‐deficient mice synergistically amplified Il6 and Tnf expression, whereas Il1b, Cxcl1, and Cxcl5 levels remained refractory to further elevation." (PMID 40810650, 2025). "The regulatory chemokines CXCL1 and CXCL16 were also increased by infection with Em though concentrations appeared to be increased more dramatically by co-infection." (PMID 39229265, 2024). "QPCR analysis showed that the expression trend of 10 genes between the co-infection and control groups (IL-17C, NFκB, AP1, C/EBPβ, CXCL1, CXCL8, MMP1, MMP3, GM-CSF, and MUC5AC) was consistent with the RNA-seq results." (PMID 31803158, 2019). "In addition, CCL4, CXCL1, and CXCL2 expression in the co-infection group was highly significant, while CX3CL1 and XCL1 expression was equivalent to that in mock control." (PMID 33968006, 2021). "In addition, type I IFN production during IAV/bacterial coinfection has been shown to suppress CCL2, CXCL1, and CXCL2 levels and subsequently inhibit the recruitment of monocytes and neutrophils." (PMID 30420852, 2018).
endometriosis (9 papers, 2007 to 2024). The growth of functional endometrial tissue in anatomic sites outside the uterine body. "A total of n = 60 women were included in the study, 31 endometriosis patients and 29 controls, and the serum levels of sCD40L and CXCL1 were measured by enzyme-linked immunosorbent assay." (PMID 27190986, 2016). "Consistently, patients with endometriosis displayed a significant higher production of CXCL1, CXCL2, and CXCL8 in the peritoneal fluid as compared to those from controls." (PMID 32334621, 2020). "In this study, we investigated the levels of sCD40 Ligand and CXCL1 in endometriosis patients and controls in order to search for possible differences in secretion levels." (PMID 27190986, 2016). "CXCL1 levels in the endometrium are elevated in patients with endometriosis and adenomyosis." (PMID 35806156, 2022). "Similarly, in the peritoneal fluid of women with endometriosis, levels of CXCL1, CXCL2, CCL2, MCP-3, and HGF were found to be significantly elevated compared to those in control individuals." (PMID 31636643, 2019). "However, our findings argue against the notion that CXCL1 has a function as a circulating regulator of systemic inflammation in endometriosis." (PMID 27190986, 2016). "CXCL1 has neutrophil chemoattractant activity via CXCR2 binding, but has been scarcely studied with respect to endometriosis." (PMID 31636643, 2019). "Moreover, cyto-hub gene analysis revealed that CSNK2A1, CSNK2A2, TOP1, PRKACA, RBM39 (plasma), ALB, ACTB, GAPDH, FN1, APOA1 (serum), S100-A9, CXCL1, IL1RN, CSTA, S100-A8 (menstrual blood) and THBS1, ALB, CD44, ANXA2, and LUM (urine) were the top 5 proteins expressed in women with endometriosis." (PMID 39061077, 2024). "On the other hand, blood CXCL1 levels in patients with endometriosis are not altered." (PMID 35806156, 2022). "Moreover, transient inhibition or reduction of miR-223 expression exacerbated endometriosis, as indicated by the histological indices, increased NLRP3, IL-1β, IL-6, and TNF-α secretion, as well as the IL-1β-inducible chemokines CXCL1 and CXCL2 mRNA transcripts." (PMID 30186287, 2018).
experimental autoimmune encephalomyelitis (9 papers, 2014 to 2025). An autoimmune demyelinating disease of the central nervous system that is produced experimentally in animals by the injection of homogenized brain or spinal cord in Freund's adjuvant. "On the other hand, it has been shown that the rise in the expression of CXCL1 in astrocytes is associated with an increased severity of experimental autoimmune encephalomyelitis (EAE) due to the increased recruitment of neutrophils." (PMID 38534751, 2024). "We previously reported an experimental autoimmune encephalomyelitis (EAE) MS mouse model with elevated serum CXCL1 that developed severe and prolonged neuron damage." (PMID 32019585, 2020). "Lif KO animals have increased expression of CXCL1, GM-CSF, RANTES/CCL5 and MIP-1β/CCL3 early during an experimental autoimmune encephalomyelitis model and reduced CCL2, CCL3, and CXCL10 at a later stage of the disease." (PMID 25277705, 2014). "In addition, Th17 cells are also capable of inducing CXCL1 and CXCL2, chemokines that are powerful attractants for polymorphonuclear cells, and of contributing much to the disruption of the BBB in experimental autoimmune encephalomyelitis (EAE)." (PMID 33281728, 2020).
Granuloma (9 papers, 2010 to 2025). A compact, organized collection of mature mononuclear phagocytes, which may be but is not necessarily accompanied by accessory features such as necrosis. "Five traits: lung granuloma necrosis (“Necr Ratio”), weight loss, MMP8, CXCL1, and IL-10 mapped to Dots8." (PMID 38861581, 2024). "Here, we find that ESX-1 promotes the production of CXCL1, 2, and 5 and the accumulation of neutrophils in granuloma core regions." (PMID 37017530, 2023). "Similarly, CXCL1/KC induction was also correlated, to a lesser degree, with the number of granulomas (r = 0.52, p<0.0001)." (PMID 22457760, 2012). "Expression of the chemokines CCL21, CXCL1, CCL7 and CCL12 showed a significant correlation with the expression of procollagen genes and resembled the recruitment of HSCs into granulomas." (PMID 20161726, 2010).
oral squamous cell carcinoma (9 papers, 2018 to 2025). "For instance, CXCL1 is an inflammatory mediator associated with metastasis of oral squamous cell carcinoma." (PMID 39199704, 2024). "C-X-C motif chemokine ligand 1 (CXCL1) and epithelial growth factor (EGF) are highly secreted by oral squamous cell carcinoma (OSCC) cells and tumor-associated macrophages, respectively." (PMID 38713320, 2024). "Further studies on oral squamous cell carcinoma cells have revealed that IL-1β mediates the formation of the chemokine CXCL1, which leads to a transactivation of EGFR via the G protein-coupled receptor CXCR2." (PMID 34205482, 2021). "Moreover, a systematic review suggests a role of inflammatory mediators as potential markers, including CXCL1, for the diagnosis and prognosis of oral squamous cell carcinoma metastasis." (PMID 39199704, 2024). "For instance, CXCL1, CXCL2, CXCL8, and CCL5 are all related to the progression and diagnosis of oral squamous cell carcinoma." (PMID 39199704, 2024). "Consistent with our findings, in previous studies, CXCL1 expression increased in cocultures of CAF and oral squamous cell carcinoma cells with IL1β, promoting tumor invasion and CAF activity." (PMID 34218518, 2021). "Moreover, oral squamous cell carcinoma cell lines, including HSC2, respond to inflammatory cytokines IL1β and TNFα with an increased chemokine expression, including CXCL1, CXCL2, CXCL8, and CCL5." (PMID 39199704, 2024). "Moreover, oral squamous cell carcinoma cell lines, including HSC2, respond to inflammatory cytokines IL1β and TNFα with an increased expression of chemokines such as CXCL1, CXCL2, CXCL8, and CCL5." (PMID 39199704, 2024). "If we relate our findings to those of others, we can acknowledge research showing that oral squamous cell carcinoma cell lines other than HSC2 and TR146 are a source of chemokines, e.g., IL1 enhanced CXCL1 expression in the dysplastic oral keratinocytes and cell lines TW2.6 and OC3." (PMID 39199704, 2024).